CD4 (CD4 molecule)
Diseases named in the same sentence as CD4 in open-access papers (continued):
Sharing a sentence is not in itself a finding about the gene and the disease.
infection (continued). "Much like their CD8+ counterparts, CD4+ TRM also produce a significant IFN-γ response during early infection." (PMID 30038624, 2018). "Shortly after infection, an increase in CD4+ cells was reported where CD4+ CD25+ clones gradually dominated indicating clonal selection." (PMID 29643841, 2018). "The risk of infection by probiotics in HIV patients appears to be small, but attention should be paid to patients with low CD4 count and disease or manipulation of the intestinal tract." (PMID 30541524, 2018). "Silencing (siRNA/shRNA post-transcriptional silencing) of filamin-A or disrupting its interaction with CD4 in target cells strongly reduced receptor co-capping and infection by inbound cell-free virus." (PMID 29401736, 2018). "A drastic reduction in EdU incorporation was observed in Txnrd1fl/fl;Cd4-Cre T cells at all time points analyzed with the largest difference at the peak of expansion (7 days post infection)." (PMID 29749372, 2018). "In contrast, Eomes does directly regulate CD4 cytotoxic molecule expression upon LCMV Cl13 infection." (PMID 30044874, 2018). "In contrast, the proportion of CD11a-CD49d- CD4 T cells, as well as the total CD4 T cell population before and after infection, was equally distributed between the WT and Il-27ra-/- compartment." (PMID 30044874, 2018). "Nef proteins that efficiently enhanced virion infectivity for TZM-bl cells by counteracting SERINC5 also potently promoted infection of primary CD4+ T cells." (PMID 30125328, 2018). "The proportion of regulatory and conventional CD4+ T cell subsets provides a metric of a balanced response to infection." (PMID 29379138, 2018). "The opposite phenomena is seen in the case of hRSV-infections, where CD4+ T cells are shown to be required for protection against reinfections." (PMID 30405642, 2018). "For example, it is well established that the pMHC-specific response magnitude of CD4+ T cells after immunization or infection directly relates to their precursor number." (PMID 29864157, 2018). "We also observed that the number of CD4+ T cells transiently dropped at the initial infection stage and fluctuated in the subsequent days." (PMID 30405615, 2018). "As a result, the frequency of Vα2+ clonotypes in env-reactive CD4+ T cells was higher following infection with WT F-MLV than with F-MLV-NB envL128I." (PMID 29951052, 2018). "Further studies are needed to determine the optimal duration of treatment in cases of localized extrapulmonary MAI infection, especially when CD4 counts are above 200 cells/uL." (PMID 29738438, 2018). "In HIV infection, the expression of CCR5 or CXCR4 chemokine receptors on target cells is the primary determinant of cell tropism, with CCR5-mediated infection of CD4+ T cells predominating early in infection." (PMID 29677122, 2018). "Data collected in the first section of the survey questionnaire included demographic information such as age, gender, marital status, occupation, educational level, employment, duration on ART, duration of infection, the most recent CD4 count." (PMID 29941015, 2018). "CD15+ granulocyte depletion from blood prior to infection with M. tuberculosis-lux impaired control of mycobacteria by 96 h, with a greater effect than depletion of CD4+, CD8+, or CD14+ cells (p < 0.001)." (PMID 29755473, 2018). "To evaluate the cellular inflammatory response during infection we also evaluated clinical hematology from the CD4 depleted and control animals on days four and eight post infection." (PMID 30212537, 2018). "Nevertheless, primate lentiviruses have evolved to circumvent this potent restriction which enables infection of macrophages and quiescent CD4+ T cells." (PMID 30656243, 2018). "Previous studies have reported that Arg59 residue of CD4 plays a critical role in the CD4 for conformational changes in gp120 during the sequential process of entry and infection by HIV-1." (PMID 29971062, 2018).
infection (continued). "Ultimately, the production of cytokines by CD4+ T cells is responsible for local control of infection." (PMID 30671055, 2018). "As we have found in B cells and DC, the mechanism of poor MΦ trans infection of autologous CD4+ T cells is a result of altered cell cholesterol homeostasis." (PMID 29643243, 2018). "When HSV-2 viral loads peak due to a new lesion, there is a delay before tissue damage and CD4+ T cell counts peak due to the nature of the tissue’s response to infection." (PMID 29698393, 2018). "The MOLT-4/CCR5 cell line expresses high levels of CD4 and supports infection by both X4-tropic and R5-tropic HIV-1, thereby providing greater uniformity for mQVOA." (PMID 30316868, 2018). "Given the propensity of HIV to replicate in GALT, it is tempting to link the preferential infection and depletion of α4β7high CD4+ T cells in the very early stages of infection, with V2-α4β7 interactions." (PMID 30153309, 2018). "Activated M1 macrophages, with CD4+ T-cells, resolve the infection by entrapping and degrading the cryptococcal propagules through the formation of granulomas." (PMID 29670625, 2018). "CD4+ T-cells play a major role in immune response and aid B cells to make antibodies, activate phagocytes, and recruit other immune cells to the site of infection/inflammation." (PMID 29632528, 2018). "As only few of the abundant number of CD4+ T cells at the site of infection express CXCR3, it seems plausible that the CXCL10/CXCR3 chemotactic axis is under regulation by DPP4 in active TB." (PMID 30026741, 2018). "The env genetic diversity or env clonal number in the plasma or cervix at very early/early infection was compared to the slopes of CD4 T cell declines and of viral RNA load increases in these patients." (PMID 29346424, 2018). "Due to the parallel expansion of CD25+Foxp3− cells during infection, this results in a small reduction in the proportion of CD4+CD25+ cells which expresses Foxp3." (PMID 28975357, 2018). "In one recent study of HIV infected women, pre-infection levels of peripheral blood α4β7high CD4+ memory T cells correlated with the rate of CD4+ T cell decline post-infection." (PMID 30153309, 2018). "Study on the lung lesions in goats revealed that the activation of CD4+ T lymphocytes plays a prominent role in the acute phase of the infection." (PMID 29967623, 2018). "Age at the time of diagnosis, smoking, baseline SCr ≥5.74 mg/dl, CD4+ T cell< 281 μl, and IV-CYC therapy were identified as risk factors for infection." (PMID 29902982, 2018). "After infection with L3, there was a progressive increase in the population of CD4+ T cells treated with PAS-5." (PMID 29843794, 2018). "Memory T‐cells have learnt this information during the primary response, and some memory CD4 T‐cells, tissue resident memory (Trm) cells, continue to reside at the infection site." (PMID 29570776, 2018). "IFNγ+ CD4 T cells were also increasingly present in the BM over the course of infection; however, the frequency and numbers of these cells dropped at d35p.i., as observed in the spleen." (PMID 29472618, 2018). "The compartment with low drug penetration, hereon referred as the drug-limited compartment, partially allows the infection of CD4 cells by the wild-type virus." (PMID 30016329, 2018). "The Ifnar1-/- mice received the CD4+T cell depleting antibody three days prior to infection and a second dose on the day of subcutaneous (SC) infection with 1x105 focus forming units (FFU) of ZIKV." (PMID 30212537, 2018). "IL-10 is upregulated during acute v2.2-1 infection, at which time it is mainly produced by CD4+ and to a lesser extent CD8+ T cells." (PMID 30619363, 2018). "By day 8 p.i., similar numbers of activated (CD44hiCD62Llo) NK1.1− and NK1.1+ CD4+ T cells were seen over the course of the infection except for day 24 when a significant reduction in NK1.1+ cell numbers occurred with no corresponding loss of NK1.1− cells." (PMID 30374346, 2018).
infection (continued). "In FV infections, IL-2 is predominantly produced by FV-specific effector CD4+ helper T cells responding to the infection." (PMID 29447279, 2018). "Dendritic cell activation of CD4 T cells in the lymph node draining a site of infection or vaccination is widely considered the central event in initiating adaptive immunity." (PMID 30524434, 2018). "Multivariate analyses found that lower baseline CD4+ cell counts and higher HIV viral load (again, markers of more advanced infection) were associated with greater gains in body weight, BMI and lean body mass." (PMID 30542325, 2018). "At d10 after WT infection of CD4+ T cell-depleted mice, all infected cells (n>100, counting samples from 6 mice) were MHC II- (WT)." (PMID 29447285, 2018). "Human infection with M. tb induced distinct, antigen-specific CD4+ TSCM cells endowed with effector functions, including expression of cytotoxic molecules and Th1 cytokines, and displayed chemokine receptor profiles consistent with memory Th1/17 cells." (PMID 29545791, 2018). "A well-known function of Nef, Env and Vpu is the downmodulation of CD4 in activated T cell infection." (PMID 29394935, 2018). "HIV increases the progression from infection to disease, especially when the CD4 counts are low, and is partially reversed with antiretroviral therapy." (PMID 29410796, 2018). "Here we extend these observations by demonstrating that in CD4 null mice, brain virus RNA levels remain at a significantly higher level than in WT mice, and that at 4 weeks post-infection infectious virus can again be detected." (PMID 29783708, 2018). "To address that, we traced back the source of the produced cytokines during Sm infection by co-staining of intracellular cytokines and Foxp3 in CD4+ T cells." (PMID 30379806, 2018). "The number of pre-Tfh cells (CD4+CD62L−CXCR5intPD-1int) was significantly elevated after 6 days of infection with PbAWT." (PMID 30006528, 2018). "Since blocking of CD200–CD200R signaling following LdWT infection correlated with the suppression of IL-10 producing CD4+ T cells, we were particularly interested to further characterize these cells." (PMID 29915577, 2018). "Remarkably, a high percentage of infant circulating CD4+ T cells that expressed CD69 at the time of the first challenge strongly correlated with a low number of challenges to infection (r = −0.75, P = 0.003)." (PMID 29359183, 2018). "The induction of a CD4 phenotype that is permissive to infection and has gut-homing capabilities, therefore, likely contribute to HIV infection and spread." (PMID 29760706, 2018). "A study using M. tuberculosis infected mice showed that the infection triggered antigen-specific CD4+ Tregs, which delayed adequate pathogen clearance and favored persistent infection." (PMID 29315226, 2018). "For example, developmentally exposed adult offspring have significantly fewer virus-specific CD8+ cytotoxic T lymphocytes (CTL) and conventional CD4+ T helper cells after infection with influenza A virus." (PMID 30412605, 2018). "The FRC-mediated trans-infection was observed with viruses produced by primary lymphocytes, likely CD4+ T cells, isolated from human tonsils." (PMID 29934525, 2018). "Immunosuppressive viruses interfere with the immune processes of their animal hosts in multiple ways; for example, HIV causes immune dysfunction of the host by interfering with the function of CD4+ cytotoxic T lymphocytes, thus facilitating pathogen infection." (PMID 29347945, 2018). "Low dose infection in the skin has recently been shown to be depended on CD4+ and CD8+ T cells 12,23,24." (PMID 30090205, 2018). "The first weeks post infection, the acute phase, are characterized by an exponential increase in viral load accompanied by a rapid depletion of CD4+ T cells, the target cells of HIV." (PMID 30050523, 2018). "Early studies defining the tropism of HIV-1 indicated that activated CD4+ T lymphoblasts were the preferred target of infection." (PMID 29433524, 2018).
infection (continued). "Altogether, these results indicate that the inoculation in the ear with S. schenckii conidia combined with the CT induces a superior DTH reaction, compared to the infection, which is dependent on circulating memory CD4+ T cells." (PMID 29946313, 2018). "Dogs in both vaccinated and unvaccinated groups mounted a significant E. chaffeensis-specific CD4 T cell response by 7–10 days after infection." (PMID 30050533, 2018). "Latent reservoirs of resting memory HIV-infected CD4 T cells are established very early after infection and result in a viral rebound upon treatment interruption." (PMID 30254642, 2018). "CD4 T cells help B cell maturation, activate cytotoxic T cells and macrophages, and recruit neutrophils to the sites of infection by releasing T cell cytokines." (PMID 30052667, 2018). "Consistent with previous findings, CD4+ T cell apoptosis was evident around day 7 p.i. and increased progressively with ongoing infection." (PMID 30462731, 2018). "Morbidity and the magnitude of antibody, CD8+ and CD4+ T cell responses after infection were measured." (PMID 29379138, 2018). "Although the initial levels of CD4+ T cells differed among the animals, they all exhibited the typical steep decline in lymphocytes shortly after infection and their CD4 levels remained low throughout the time course." (PMID 29437924, 2018). "Due to a low contribution of IgG in primary infection clearance, the authors suggested a role of IgG together with CD4+ T cells in generating a memory and therefore a second immune response." (PMID 30050523, 2018). "Flow cytometric analysis 21 days post infection showed that expression of CD200R on activated CD4+ T cells was reduced upon treatment with α-CD200 antibodies but not in isotype-treated controls indicating the specificity of the CD200 blocking antibodies." (PMID 29915577, 2018). "The invasion and infection of CD4+ T lymphocytes by HIV-1 is a complex process involving many cellular events triggered after the first Env-CD4 interaction that have been the subject of many studies." (PMID 29636433, 2018). "The same LRAs and combinations were next tested after infection of human CD4+T cells in vitro with HIVGKO." (PMID 29714165, 2018). "The DCIR expression was detected on DCs, monocytes, macrophages, B-lymphocytes, and granulocytes such as DC-SIGN, DCIR captures HIV-1 and promotes infection in cis and trans of CD4 + T-cells from immature DCs." (PMID 29632536, 2018). "Infection of CD4-positive cells does not only kill the infected cells after virus production, but also kills uninfected CD4-positive cells via bystander mechanisms." (PMID 29662026, 2018). "Although TH17 cells are markedly regulated by IL-12 family cytokines in the murine infection and CD4+ T cells of this subset are a part of the inflammatory infiltrates in such model, the functional importance of this subpopulation has not been clarified yet." (PMID 30197647, 2018). "In our study (subset of 80 of 286 patients), we observed a similar trend in the differential CD4 T cell decline based on HIV subtype infection, e.g. subtype C infections had the slowest loss in CD4 T cells." (PMID 29346424, 2018). "Because the new model of direct resting CD4+ T cell infection is based in a lymphoid context, studying T cell communication with microvascular EC is of higher in vivo relevance." (PMID 30285810, 2018). "Second, CD4+ T cells of the gut are likely to be more vulnerable to infection than their peripheral blood counterparts." (PMID 30440043, 2018). "At 60 h post-infection, the activated Smarta CD4+ T cells were mostly in the 4th and 5th divisions, a window in which nascent TH1 and TFH cells emerge, with nascent TH1 expressing higher Blimp1-YFP and nascent TFH cells being Blimp1-YFPlo." (PMID 30575739, 2018).
infection (continued). "Here we asked if CD4+ T cell responses to immunization or infection increase with aging since the magnitude of a CD4+ T cell response to a foreign pMHCII is proportional to the size of the precursor population in adult mice." (PMID 29864157, 2018). "Of note, a specific DC subset expressing both CD14 and CD16 was demonstrated to have a high capacity to transmit infection to CD4+ T-cells through DC-SIGN expression." (PMID 29415518, 2018). "In contrast to the VS, CD4 and Env are dispensable for the formation of the IS, but are necessary for viral fusion and productive infection of T cells." (PMID 30055632, 2018). "CD4+ T cells isolated from the lungs of Nlrc3-/- mice showed stronger expression of intracellular IFN-γ, TNF-α and IL-17A after restimulation than that showed by CD4+ T cells isolated from lungs of WT mice at 3 weeks post-infection (w.p.i.)." (PMID 30133544, 2018). "The elevated hexokinase activity and HK1 expression levels were the most significant alterations to glycolysis in response to infection of CD4+ T cells with HIV-1 that we observed in the course of our investigations." (PMID 29518929, 2018). "The effects of diminished CD200–CD200R signaling by LdCen−/− were most evident in the suppression of IL-10-producing CD4+ T cells that helped enhance more Th1 cytokine producing and multi-functional T cells compared to wild-type infection." (PMID 29915577, 2018). "We previously reported moderate upregulation of intracellular and surface expressed GLUT1 in response to infection of primary human CD4+ T cells with HIV-1, as assessed by flow cytometry." (PMID 29518929, 2018). "Altogether, these data show that P25 mice control infection similarly to WT, although with a distinct CD4+ T cell activation and cytokine producing profile." (PMID 29499041, 2018). "In this infection model, bacterial control depends on the formation of listeria-specific CD4+ and CD8+ T cells." (PMID 29742141, 2018). "T cell activation, as measured by the downregulation of CD62L expression in CD44+CD4+ T cells, was reduced early during infection, and restored to WT levels at the later stage." (PMID 29675017, 2018). "While the infection preferentially induced a high production of IFN-γ by CD4+ T cells, the skin immunization with iC+CT mainly induced production of IL-17." (PMID 29946313, 2018). "Localization of antigen-specific CD4+ T cells at the site of infection in the lung parenchyma is of ultimate importance for disease protection after vaccination." (PMID 30555488, 2018). "HIV latency in resting CD4+ T cell represents a key barrier preventing cure of the infection with antiretroviral drugs alone." (PMID 29800728, 2018). "Eight days post infection we detected virus in the peripheral organs including liver, spleen, and kidneys of both the CD4 depleted and control animals." (PMID 30212537, 2018). "RF of the IgM isotype (IgM-RF), for example, promotes phagocytosis and the removal of antigen-antibody complexes in the course of infection, fixation of complement, and enhancing B cell antigen uptake and presentation to CD4+ T cells." (PMID 30693002, 2018). "Here, we have studied the expression and function of natural cytotoxicity receptor NKp44 upon NK-astrocytes interactions in the presence or absence of an HIV peptide (HIV-3S peptide) shown to induce NK cell killing of CD4+ T cells during HIV–infection." (PMID 29447242, 2018). "(C) Comparison of HIVDuoFluoI and HIVGKO infection profiles by flow cytometry in activated primary CD4+ T-cells (4 days post-infection)." (PMID 29714165, 2018). "A possible model to explain our collective results following PE243 infection is the one in which CD4+ TFH cells induce the differentiation of B cells into GC-B cells in a mechanism dependent of IFNγ." (PMID 30087337, 2018). "To date, the consequences of these changes for CD4+ T cell responses to immunization or infection remains unexplored." (PMID 29864157, 2018).